ALB (albumin)
Diseases named in the same sentence as ALB in open-access papers (continued):
Sharing a sentence is not in itself a finding about the gene and the disease.
Hypoalbuminemia (continued). "Five‐year relapse‐free survival rates of hypoalbuminemia and normal albumin patients were 78.9% and 73.5%, respectively (HR 1.28, 95% CI 1.04‐1.56, P = .020), and five‐year OS rates were 78.0% and 60.0%, respectively (HR 1.75, 95% CI 1.49‐2.08, P < .0001)." (PMID 33860145, 2021). "In post hoc analysis, we found the difference between patients with normal albumin concentration (≥3.5 g/dL) and severe hypoalbuminemia (<2.5 g/dL) only (log-rank test statistic = 1.51; p = 0.015)." (PMID 33801869, 2021). "Serum albumin of 2.45 g/dL was identified as the cut-off value to define hypoalbuminemia that was optimal for the prediction of short and long-term mortality in patients with septic shock." (PMID 33925831, 2021). "This drug induced hypoalbuminemia manifesting a more than 60% decrease in serum albumin concentration." (PMID 34071680, 2021). "This review focusses on albumin in the context of infections, including the roles of hypoalbuminemia and of adjunctive treatment with HAS." (PMID 33925831, 2021). "This study found similar results; patients with hypoalbuminemia had a higher complication rate (50%) as compared to those with normal albumin (37%)." (PMID 34868791, 2021). "The impact of hypoalbuminemia on survival is not limited to heart failure with reduced ejection fraction as albumin levels were predictive of mortality in patients with heart failure with preserved ejection fraction." (PMID 33805128, 2021). "This especially applies to certain conditions like hypoalbuminemia, which is why total serum calcium levels can be corrected for albumin concentrations." (PMID 33510279, 2021). "Hypoalbuminemia (serum albumin levels below 35 g/L) is more severe in critically ill patients and is associated with poor outcomes." (PMID 33968298, 2021). "Should albumin be initiated in an attempt to correct hypoalbuminemia or as a volume replacement fluid?" (PMID 33644843, 2021). "Consistent with previous studies, we found out that hypoalbuminemia (albumin cut-off point of 39.6) and D-dimers acted as independent predictors of PFS and OS." (PMID 32771026, 2020). "The present study analyzed changes in albumin levels in hospitalized patients by assessing the prevalence of preexisting hypoalbuminemia at the time of discharge from hospital." (PMID 33261019, 2020). "Based on clinical findings of significant proteinuria (urine protein and creatinine ratio of 11.4), hypoalbuminemia (serum albumin of 2 g/dl), and hypercholesterolemia (total cholesterol of 384 mg/dl), he was diagnosed with nephrotic syndrome." (PMID 32974243, 2020). "On admission, there was decreased level of albumin in the older group with 18 (5.9%) older patients developing hypoalbuminemia (albumin < 30 g/L), suggesting a poor nutrition status of older patients." (PMID 33032534, 2020). "Hotelling's t analysis revealed significant differences among the presurgical albumin infusion (B), presurgical normal protein diet (C), and hypoalbuminemia (D and E) diet groups in terms of serum levels of albumin, TNF-α, IL-1, IL-6, CRP, and MMP-8 (P=0.01)." (PMID 32518615, 2020). "Hypoalbuminemia is well known predictor for the short-term prognosis in patients with ADHF27,28, although albumin level is influenced by hemodilution, renal loss, and shortened half-life due to severe illness." (PMID 32094392, 2020). "A higher mean value of total white blood cell (WBC) count was observed among patients with hypoalbuminaemia (p < 0.0001) and reversal of albumin-to-globulin ratio (p < 0.0001) when compared to patients with normal values, respectively." (PMID 33312698, 2020). "As an established risk factor for sepsis and mortality in critically ill patients, hypoalbuminemia needs to be corrected by albumin treatment." (PMID 32576140, 2020). "Kaplan-Meier curves were used to estimate survival based on preoperative albumin levels of ≤3.5 g/dL (hypoalbuminemia) versus > 3.5 mg/dL." (PMID 32778080, 2020).
Hypoalbuminemia (continued). "On the other hand, in a randomized controlled trial on off-pump coronary artery bypass surgery (110 patients/group), preoperative correction of hypoalbuminemia with exogenous albumin protected from acute kidney injury." (PMID 32111230, 2020). "This study also reveals that those hospitalized LF infected patients with hypoalbuminemia and/or reversal of albumin-to-globulin ratio tend to have leucocytosis and experience prolonged duration of illness." (PMID 33312698, 2020). "As indicators of hepatic dysfunction, patients with hypoalbuminemia (albumin < 3 g/dL) or coagulopathy (international normalized ratio > 1.5) had significantly higher mortalities than those of their counterparts (p = 0.005 and p < 0.001, respectively)." (PMID 32948044, 2020). "In this study, patients with hypoalbuminemia (< 3.5 g/dL; N = 9) had a similar average SC as compared with patients with normal albumin levels (0.89 vs. 0.88)." (PMID 32223067, 2020). "Hypoalbuminemia, defined as serum albumin levels <3.5 g/dL, is common among hospitalized patients and is associated with mortality and increased risk for various diseases, including heart failure, cirrhosis, and nephrotic syndrome." (PMID 31945744, 2020). "Nevertheless, IS was associated with a slightly higher hazard ratio for progression of CKD in patients with proteinuria, while the effect of IS on progression depending on serum albumin was decreased in hypoalbuminemia." (PMID 33108385, 2020). "Hypoalbuminemia was universal in all patients and this probably because of significant systemic inflammation which will lead to leakage of albumin from blood vessels to tissues." (PMID 33240687, 2020). "In indexes of liver enzymes and function, patients with HH had significant degrees of ALB reduction compared with that non-HH group (P < 0.05) and the concentration of ALB has reached the level of hypoalbuminemia (ALB<30 g/L)." (PMID 33681238, 2020). "Out of 83 recruited participants with complete records; 66 (79.5%) had hypoalbuminaemia, 74 (89.2%) had reversal of albumin-to-globulin ratio." (PMID 33312698, 2020). "Other explanations for hypoalbuminemia in cancer patients include a higher vascular permeability due to cytokines and a subsequent leaking of albumin in the extracellular compartment." (PMID 35847697, 2020). "At present, corrected hypoalbuminemia via intravascular albumin infusion to improve outcome remains controversial." (PMID 33203167, 2020). "In this study, the average age of included patients was 45 years, and only 2% of them had hypoalbuminemia (25/1259) in the context of routine test of preoperative albumin." (PMID 33004062, 2020). "These were poor function class (NYHA class III/IV), tachypnea (RR > 24 per minute), anemia (Hb < 10 mg/dL), and hypoalbuminemia (serum albumin < 3.5 g/dL)." (PMID 32867269, 2020). "In this study, we sought to determine the roles of albumin in wound healing, which is infused both pre- and postoperatively in malnourished patients presenting with hypoalbuminemia." (PMID 32518615, 2020). "Pre- and postoperative albumin infusion and normal protein nutrition were administered in the attempt to correct the hypoalbuminemia, and we found that these treatments significantly increased serum albumin levels." (PMID 32518615, 2020). "Considering low hypoalbuminemia mechanisms, monitoring the albumin serum level and giving albumin supplementation in case of low level appeared to be an adequate strategy to decrease the risk." (PMID 33203417, 2020). "Albumin values of 3.5 g/dL and above were accepted normal and below 3.5 g/dL were accepted hypoalbuminemia." (PMID 32348706, 2020). "Improved prognostic accuracy was consistent across subgroups of lactate levels (lactate <2 mmol/L and lactate ≥2 mmol/L), hypoalbuminemia (albumin <3 g/dL) and renal dysfunction." (PMID 33072780, 2020).
Hypoalbuminemia (continued). "Nearly half of the sample already had hypoalbuminemia at their first visit to the hospital (42.9% mild and 9.6% marked), while only slightly less than 45% of patients had a normal level of albumin." (PMID 33261019, 2020). "It has been reported that administering serum albumin to cirrhotic patients with hypoalbuminemia corrects circulatory insufficiency and improves the survival rate." (PMID 32051434, 2020). "Our analysis also strengthens the case for the evaluation of albumin infusion aimed at the correction of hypoalbuminemia." (PMID 33063792, 2020). "Six hundred and twenty-four patients with preoperative albumin level data were identified, of which the prevalence of hypoalbuminemia (serum albumin < 3.5 g/dL) is 2.7%." (PMID 32660593, 2020). "In this study, we sought to establish the role of albumin in regulating the transduction factors and proteins that can affect wound healing in hypoalbuminemia." (PMID 32518615, 2020). "Albumin is an indicator of a patient’s nutritional status, and hypoalbuminemia is considered as a potential biomarker for sarcopenia." (PMID 32604773, 2020). "Hyperproteinaemia (61.1%) with hypoalbuminaemia (22.2%) and hyperglobulinaemia (63.8%) with a low albumin:globulin ratio (38.9%) were prominent features of blood biochemistry reports." (PMID 32400257, 2020). "Nephrotic syndrome represents a constellation of symptoms including peripheral edema, heavy proteinuria, hypoalbuminemia, and often hyperlipidemia and is thought to result from increased glomerular permeability to albumin and other plasma proteins." (PMID 32849923, 2020). "Laboratory data at onset revealed anemia (hemoglobin, 7.8 g/dL), hypoalbuminemia (albumin, 1.5 g/dL), and elevated serum levels of IgG4 (1080 mg/dL) and CRP (5.05 mg/dL)." (PMID 31951598, 2020). "Despite this, we still need to be wary of hypoalbuminemia with albumin levels < 3.0 g/dl after surgery." (PMID 33203417, 2020). "In the training cohort, 163 (58.6%) patients had low serum albumin at diagnosis, and 80 of them were present with consecutive hypoalbuminemia at EoT." (PMID 33585232, 2020). "Traditionally, albumin has been regarded as a nutritional marker, a fact that leads to the administration of enteral or parenteral nutritional therapy in patients with hypoalbuminemia in various situations in clinical practice, e.g., preoperatively." (PMID 32351914, 2020). "Patients with postoperative hypoalbuminemia had significantly longer postoperative LOS than those patients with higher postoperative albumin levels (≧3.5 g/dL; Mann-Whitney test, p = 0.001)." (PMID 32673371, 2020). "There is a baseline hypoalbuminaemia and reversal of albumin-to-globulin ratio among confirmed LF infected patients." (PMID 33312698, 2020). "The significance of serum ALB levels is limited to varying degrees of hypoalbuminemia, as, except for cases of acute dehydration, hyperalbuminemia does not occur." (PMID 33297385, 2020). "An average of 2.3 ± 3.3 units of RBC and 14.2 ± 32.3 g albumin were administrated to patients presented anemia or hypoalbuminemia." (PMID 32576140, 2020). "There is a baseline hypoalbuminemia and reversal of albumin-globulin ratio among confirmed LF-infected patients." (PMID 33312698, 2020). "These modes of action explain the observed acceleration of wound healing by day 3 and peak wound healing rate by day 5 after surgery for the albumin infusion and normal protein diet groups relative to the hypoalbuminemia group." (PMID 32518615, 2020). "Hospitalization worsened the patients’ hypoalbuminemia, with more than 70% of the sample having a low level of albumin (either marked or mild) at the time of discharge, with elderly patients accounting for nearly 50% of the sample." (PMID 33261019, 2020).
Hypoalbuminemia (continued). "In connection with the role of hypoalbuminemia, albumin is a known prognostic factor in HCC, specifically included in staging systems like the Cancer of the Liver Italian Program (CLIP) score or the ALBI grade and in many other staging systems." (PMID 32379785, 2020). "In a meta-analysis of observation studies, the cut-offs for defining hypoalbuminemia varied, but low serum albumin concentrations were clearly identified as an independent risk factor for AKI35." (PMID 31792326, 2019). "Patients with hypoalbuminemia had higher mortality than patients with normal albumin levels (48% vs. 23%, p = 0.004)." (PMID 31095609, 2019). "Albumin-correction AG (cAG)** identifies most situations where there is accumulation of an anion other than chloride and hypoalbuminemia." (PMID 31418093, 2019). "A multi-institutional study showed preoperative hypoalbuminemia (serum albumin < 30 g/L) was an independent predictor for development of superficial and deep surgical site infection and prolonged hospital stay following gastrointestinal surgery." (PMID 31253199, 2019). "Postoperative complications (mainly mild complications) were observed in 55.6% and 39.4% of patients with hypoalbuminemia and normal albumin levels, respectively (p = 0.345)." (PMID 31468203, 2019). "The main study outcomes are the incidence of acute anemia requiring transfusion and incidence of hypoalbuminemia requiring albumin supplementation." (PMID 31045842, 2019). "Prospective trials are needed to further identify the association between hypoalbuminemia and AKI and explore the potential beneficial effects of albumin infusion or specific nutritional therapy on postoperative AKI prevention." (PMID 31477030, 2019). "Low serum albumin reflects the nutritional status of patients or an increased leakage of albumin into the extravascular space, which results in hypoalbuminemia, pleural effusion, or edema." (PMID 31217896, 2019). "The purpose of this study was to apply propensity score matching to this robust database to compare the postoperative outcomes in colorectal cancer patients with mild hypoalbuminemia to those with normal serum albumin." (PMID 31253199, 2019). "Patients suffering from these diseases also typically had hypoalbuminaemia, with blood ALB concentrations of 10–23 g/L, which usually resolved after several weeks of treatment with glucocorticoids, immunosuppressants and diuretics." (PMID 30727992, 2019). "Yet, procoagulant factors, including factors V, VII, VIII, and the von Willebrand factor, have been reported to increase due to hypoalbuminemia, because they are normally bound to albumin." (PMID 31336742, 2019). "Taking the albumin level into account in the calculation of AG unmasks plasma acids when there is hypoalbuminemia." (PMID 31418093, 2019). "Among the 28 patients in whom albumin levels were evaluated, 19 developed hypoalbuminemia and 15/19 (78.9%) had an incomplete form." (PMID 31493782, 2019). "After adjusting the crude model, patients in the hypoalbuminemia group were 3.5 times more likely to have poor neurologic outcome than were those in the normal albumin group (OR 3.526, 95% CI 1.388–8.956, p=0.008)." (PMID 31565439, 2019). "A total of 5779 HF patients were included in the study; mean follow‐up was 576 days; median serum albumin was 4.0 g/dL (interquartile range 3.7‐4.2), and 12% of the patients had hypoalbuminemia (albumin<3.5 g/dL)." (PMID 30637771, 2019). "After matching, the patients with mild hypoalbuminemia still had significantly higher in-hospital mortality rates compared with those with normal albumin levels (2.3% vs. 1.3%; OR = 1.74; p < 0.001)." (PMID 31253199, 2019). "Although albumin concentrations (28 ± 3 g/L) were also stable, their levels were low in relation to the reference range and identified the pathological nature of hypoalbuminemia." (PMID 31711426, 2019).
Hypoalbuminemia (continued). "In vulvar cancer patients with hypoalbuminemia compared to patients with normal serum albumin concentrations, 5-year overall survival (OS) rates were 17.1% and 58.6%, respectively (p < 0.004)." (PMID 31468203, 2019). "In the present study, low albumin and not only hypoalbuminemia was a strong predictor of reduced survival and increased hospitalizations." (PMID 30637771, 2019). "In our department, for preoperative preparation, preoperative hypoalbuminemia in certain patients had been always remedied before hepatectomy by the infusion of albumin." (PMID 31488117, 2019). "Lower baseline albumin was associated with mortality independently of the CardShock risk score, the IABP-SHOCK II score and the variables associated with hypoalbuminemia." (PMID 31095609, 2019). "In our study, human albumin was prescribed at the discretion of attending physicians, and the primary indications for the use of albumin infusion mainly included post-paracentesis, ascites, and hypoalbuminemia." (PMID 31596729, 2019). "The inflammatory state resulting from bacterial infection, which leads to the production of IL-1, TNF, and other cell mediators, can interfere with liver albumin synthesis, resulting in hypoalbuminemia." (PMID 31467670, 2019). "The etiologies of hypoalbuminemia include malnourishment, hepatic impairment, decreased hepatic synthesis of albumin due to interleukin (IL)-1, IL-6, and tumor necrosis factor (TNF)-α, and protein loss via the kidney or gastrointestinal tract." (PMID 31731708, 2019). "We reasoned that since hypoalbuminemia was observed in our septic shock model and that albumin is a fatty acid transporter, it would have been plausible to find an association between these molecular species." (PMID 30745875, 2019). "In a meta-analysis of hypoalbuminemia in acutely ill patients, it was estimated that each 10 g/L decrease in serum albumin concentration increased the odds of mortality by 137%." (PMID 31095609, 2019). "Patients in the hypoalbuminemia group were 3.5 times more likely to have poor neurologic outcome than were those in the normal albumin group (Model I)." (PMID 31565439, 2019). "We matched mild hypoalbuminemia patients and patients with normal serum albumin levels using a propensity score matching method to decrease the biases associated with the selecting of two groups with significant differences in other clinical characteristics." (PMID 31253199, 2019). "Nevertheless, long standing clinical experience has shown that treatment with diuretics as well as albumin administration results in diuresis and natriuresis in patients with edema and hypoalbuminemia." (PMID 31336742, 2019). "In chronic illness hypoalbuminemia has been attributed to decreased albumin synthesis due to wasting and cachexia, although recent literature suggests that increased catabolism is more often the cause." (PMID 31095609, 2019). "Six were excluded due to severe hypoalbuminemia (4 for serum albumin < 2.8 g/dL) or comorbidities (1 for end stage of chronic renal failure, 1 for cognitive dysfunction, no others were found)." (PMID 31481078, 2019). "Hypoalbuminemia (serum albumin concentration < 3.5 g/dL) is most commonly used serum marker of malnutrition." (PMID 31481078, 2019). "In our cohort, we found major wound complications in 13.7% (n = 14), in 22.2% and 12.9% of patients with hypoalbuminemia and normal albumin levels, respectively (p = 0.438)." (PMID 31468203, 2019). "Severe complications (CDC3-5) were rare and observed in 0% and 4.3% of patients with hypoalbuminemia and with normal albumin serum levels, respectively." (PMID 31468203, 2019). "Chronic inflammation has been suggested to induce hypoalbuminemia through inhibition of albumin synthesis and stimulation of its catabolism." (PMID 31181128, 2019). "Mean serum albumin was lower in ranges of hypoalbuminemia in patients in CAPD (2.9 ± 1.1 g/dL) than in HD (3.6 ± 0.6 g/dL) and in CT children (3.5 ± 0.8 g/dL; ANOVA, p = 0.061)." (PMID 31694220, 2019).